VWF (von Willebrand factor)
Diseases named in the same sentence as VWF in open-access papers (continued):
Sharing a sentence is not in itself a finding about the gene and the disease.
Thrombocytopenia (continued). "During the late stage of the disease, critically ill patients show cytokine storm, still high levels of P-selectin and D-dimer, while fibrinogen and VWF decrease because they are depleted by damaged endothelial cells or hyperactivated platelets that, at this stage, show thrombocytopenia." (PMID 34948438, 2021). "Once the experimental model of BjV preincubated with ABA showed that botrocetin was not involved in the development of thrombocytopenia, to double prove that botrocetin was not involved therein, mice that are deficient in VWF were also used." (PMID 34478462, 2021). "Severe dengue cases have been associated with exocytosis of Weibel–Palade bodies as well as increased circulating levels of VWF that may contribute to thrombocytopenia and complications in severe dengue cases." (PMID 33322218, 2020). "Depending on the direction, dysregulation of fibrin(ogen) D-dimer, VWF and P-selectin may result in either hypercoagulation or excessive bleeding and thrombocytopenia." (PMID 32708334, 2020). "Specifically, we hypothesized that circulating platelets in severe leptospirosis are activated and have bound more VWF and that both these processes contribute to thrombocytopenia and platelet dysfunction, especially in those with bleeding complications." (PMID 28934202, 2017). "These conditions differ from classic type 2B VWD not only in the associated VWF multimer pattern, but also in that patients never suffer from thrombocytopenia." (PMID 28640903, 2017). "The bleeding phenotype in VWD-type 2B is often explained by 1) the unavailability of GPIbα due to constitutively bound VWF 2B mutant 2) the absence of HMW-VWF multimers, the most functionally effective forms of VWF and 3) the moderate-to-severe thrombocytopenia observed in these patients." (PMID 25297919, 2015). "Our group has indeed generated a mouse model of VWD-type 2B (based on hydrodynamic injection of a p.V1316M VWF-expressing plasmid) which reproduces the clinical phenotype of human patients with a severe bleeding phenotype, thrombocytopenia, circulating aggregates and giant platelets." (PMID 25297919, 2015). "High VWF concentrations may occur under inflammatory conditions and may aggravate thrombocytopenia in VWD-type 2B." (PMID 26645283, 2015). "The second possibility is that thrombocytopenia may be explained by the presence of circulating VWF/platelet aggregates (secondary to spontaneous platelet binding of mutant VWF), undergoing clearance from plasma." (PMID 25297919, 2015). "To investigate whether apoptosis participates in thrombocytopenia in VWD-2B patients, we searched for apoptotic markers in platelets isolated from two patients with a severe VWF-type 2B mutation (VWF/p.V1316M)." (PMID 26645283, 2015). "In conclusion, our results strongly suggest that apoptosis is unlikely to contribute significantly to thrombocytopenia in VWD-2B with the severe mutation VWF/p.V1316M." (PMID 26645283, 2015). "Recent data provide evidence that an altered ADAMTS13 activity and a subsequent shift in the multimeric pattern of VWF may contribute to thrombocytopenia and microcirculatory failure due to TMA, which results in organ dysfunction including AKI." (PMID 25960882, 2014). "Thrombocytopenia, thrombocytopathy, or impaired function of vWF can disrupt primary hemostasis." (PMID 25397410, 2014). "Levels of von-Willebrand factor cleaving protease are not consistently altered in CR-MAHA associated with thrombocytopenia." (PMID 24490094, 2013). "To date, the best-studied vWF-binding CLPs isolated from pitviper venom are botrocetin and aspercetin, both of which induce thrombocytopenia and contribute to systemic bleeding by binding with the A1 domain of vWF and enhancing its affinity for platelet glycoprotein Ibα." (PMID 21731638, 2011). "These mice developed thrombocytopenia and VWF-rich thrombi in the kidney." (PMID 21720563, 2011).
Thrombocytopenia (continued). "The lack of renal failure and significant thrombocytopenia or hemolytic anemia in vivax-associated coma does not suggest a thrombotic thrombocytopenic purpura-like syndrome due to altered vWF/ADAMTS13." (PMID 21666785, 2011). "We had hypothesised that increasing VWF levels would compensate for thrombocytopenia." (PMID 39157598, 2024). "In addition, platelet hyperactivity, as evidenced by increased urine excretion of 11-dehydro-thromboxane B2, elevated p-selectin expression on the platelet surface, and increased interaction of platelets with von Willebrand factor, was noted in cirrhotic patients with thrombocytopenia." (PMID 37296908, 2023). "Thus, “DIC” has been newly defined as EA-VMTD, which explains not only microvascular microthrombosis (i.e., VMTD), but also confirms the molecular changes associated with the disease (i.e., thrombocytopenia, increased activity of FVIII, and overexpression of ULVWF/VWF antigen)." (PMID 36143988, 2022). "In the critically ill patients, D-dimer and P-selectin levels are high while fibrinogen and VWF levels are decreased as these molecules are depleted from either circulation or the damaged endothelial cells and hyperactivated platelets that now show thrombocytopenia." (PMID 32708334, 2020). "However, VWF antigen levels did not correlate with platelet counts implying that thrombocytopenia in acute melioidosis has an alternative cause." (PMID 28296884, 2017). "In addition, given the presumed role of excessive VWF-platelet interaction in thrombocytopenia in severe leptospirosis, novel therapies aimed at preventing this interaction, including recombinant ADAMTS13, might also have some therapeutic value." (PMID 28934202, 2017). "However, type 2B or platelet type vWF disease due to a defect of platelet-vWF interactions is characterized by abnormally increased aggregation using low concentrations of ristocetin, with possible thrombocytopenia and platelet clumping." (PMID 28820484, 2017). "We hypothesized that the hemorrhagic complications are not only related to thrombocytopenia, but also to platelet dysfunction, and that increased binding of von Willebrand factor (VWF) to platelets is involved in both platelet dysfunction and increased platelet clearance." (PMID 28934202, 2017). "He exhibited prolonged PT, thrombocytopenia, and elevated factor VIII and von Willebrand factor levels, findings consistent with copper-induced hepatic injury and coagulopathy." (PMID 40421351, 2025). "Coagulopathy is characterized by mild thrombocytopenia, mildly prolonged prothrombin time, high levels of D-dimer, and increased levels of fibrinogen, factor VIII, and von Willebrand factor." (PMID 40502723, 2025). "A 64-year-old male patient presented with thrombocytopenia, normal routine hemostasis results, and normal VWF antigen and factor VIII levels but reduced von Willebrand factor (VWF) activity (31 IU/dL)." (PMID 39228434, 2024). "One patient had a reduced vWF:Ag (nadir at 0.35), KMP led to thrombocytopenia (17 and 22 G/L, respectively), and DIC with elevated D-dimers and reduced fibrinogen in both patients." (PMID 36551267, 2022). "Certainly, the overexpression of the ULVWF/VWF antigen and increased factor VIII activity triggering thrombocytopenia are the result of endothelial damage, and they are the pathognomonic diagnostic markers for endotheliopathy." (PMID 36143988, 2022). "We found eight proteins (ITGA2B, ITGB3, VWF, PLEK, TNF, TLR2, BCL2 and BCL2L1) were the core targets of DMAG for the treatment of thrombocytopenia." (PMID 34837956, 2021). "Coagulopathy in a cirrhotic patient is related to a reduction of coagulation factors, and the presence of anti-coagulants, thrombocytopenia, deficit of factor VII, and increased plasma levels of coagulation factor VIII and Von Willebrand factor." (PMID 33620540, 2021).
Thrombocytopenia (continued). "Decreased ADAMTS13 and increased VWF levels are relevant in TTP, which clinically manifests itself as thrombocytopenia, micro-angiopathic hemolytic anemia, fever, neurological symptoms and renal insufficiency due to the formation of microthrombi." (PMID 34134634, 2021). "It is known that in patients with liver cirrhosis, thrombocytopenia is rebalanced by increased levels of factor VIII and von-Willebrand factor and decreased levels of ADAMTS13." (PMID 32807080, 2020). "ARC1779 was able to reverse thrombocytopenia in VWD type 2B, a condition characterized by excessive binding of VWF to platelets." (PMID 30849118, 2019). "Von Willebrand factor multimers are prothrombotic, thus ADAMTS13 inhibition leads to microthrombi formation, microangiopathic hemolytic anemia, thrombocytopenia and multiple organ injury, including renal injury." (PMID 30073173, 2018). "Eight of the 21 type 2B patients lacking in large VWF multimers had low platelet counts under basal conditions, the lowest (51.0+/-20.1 x 103/μL) being identified in the three patients carrying the p.V1316M mutation, who also had giant platelets and persistent thrombocytopenia." (PMID 28640903, 2017). "Measurements of vWF and ADAMTS13 concentrations and activity would have defined the extent of this pathway’s contribution to the pathogenesis of thrombocytopenia." (PMID 25907925, 2015). "In patients with severe sepsis and severe malaria, a similar imbalance in VWF and ADAMTS-13 was found and this was considered to be related to thrombocytopenia and organ dysfunction." (PMID 22563509, 2012). "High circulating levels of VWF in its active conformation, together with low ADAMTS-13 activity levels, are likely to contribute to the thrombocytopenia and complications of dengue." (PMID 22563509, 2012). "VWF knockout mice showed no significant thrombocytopenia post-adenovirus, suggesting VWF and P-selectin mediate platelet clearance." (PMID 40733710, 2025). "Additionally, elevated levels of von Willebrand factor (vWF) and factor VIII, both primarily of endothelial origin, contribute to a hypercoagulable state, particularly in the presence of thrombocytopenia and qualitative platelet dysfunction." (PMID 41228207, 2025). "This partial hemostasis due to lone activation of the ULVWF path is characterized by consumptive thrombocytopenia, overexpressed ULVWF/VWF/VWF antigen and increased activity of FVIII due to their endothelial release, resulting in relative ADAMTS13 insufficiency." (PMID 36143988, 2022). "Hyper-coagulable parameters include the prolongation of prothrombin time and partial thromboplastin time and the elevation of fibrinogen, d-dimer, and von Wille-brand factor (vWF) activity without profound thrombocytopenia." (PMID 35274054, 2022). "PF4 and VWF may also form complexes; recognition of PF4-VWF complexes by heparin-induced thrombocytopenia antibodies contributes to thrombus propagation." (PMID 36131342, 2022). "Surprisingly, none of these subjects exhibited thrombocytopenia suggesting the absolute level of vWF:Ag alone does not lead to TTP." (PMID 36467834, 2022). "The aptamer-based anti-von Willebrand factor (ARC1779) is a potent inhibitor of the VWF A1 domain interaction with GPIb and effectively prevents the consumption of VWF and platelets in response to desmopressin in VWD type 2B and prevents desmopressin-induced thrombocytopenia in VWD type 2B." (PMID 35056696, 2022). "Although botrocetin showed no relevant role in the development of thrombocytopenia, the findings shown herein indicate that it alters VWF levels and function." (PMID 34478462, 2021). "Regardless of the presence of VWF in circulation, BjV induced the same proportion of thrombocytopenia in both strains over time (p = 0.072), and platelet counts in the BjV group was always lower than that of the respective controls." (PMID 34478462, 2021).
Thrombocytopenia (continued). "In conclusion, our results show that botrocetin is not the main toxin that induce thrombocytopenia, and that VWF is consumed and cleaved during envenomation by B. jararaca snakes, similarly to what happens in acquired or type 2A VWD." (PMID 34478462, 2021). "A previous study also reported that purified botrocetin did not cause thrombocytopenia in models of VWD, depending thereby on the presence of circulating VWF." (PMID 34478462, 2021). "All the patients with type 2B VWD and a normal VWF multimer pattern had normal platelet counts, ranging from 193 x 103μL to 322 x 103/μL under basal conditions, and they developed no thrombocytopenia at any time after DDAVP was administered." (PMID 28640903, 2017). "In conclusion, the current view for the bleeding phenotype in VWD-type 2B explained on one hand by the absence of the highly hemostatic HMW VWF multimers and on the other hand by thrombocytopenia remains valid." (PMID 25297919, 2015). "In conclusion, our data show that WPB exocytosis of VWF in its active conformation and consumption of VWF and ADAMTS-13 are prominent phenomena in severe dengue, which may contribute to thrombocytopenia and organ dysfunction." (PMID 22563509, 2012). "In contrast, animals with NiV infection that survived did not exhibit marked evidence of thrombocytopenia despite showing increased/decreased levels of fibrinogen and VWF antigen levels during the acute phase of disease that returned to normal during convalescence." (PMID 41460894, 2025). "In addition to inflammation, endotheliopathy is characterized by the increased activity of FVIII, overexpressed ULVWF/VWF antigen, and insufficient ADAMTS13 activity, which activates the ULVWF path of hemostasis, leading to consumptive thrombocytopenia and microthrombosis." (PMID 36143988, 2022). "In sum, there were no diagnostic clues for classic TMA (lacking schistocytes, normal or elevated haptoglobin levels, no severe thrombocytopenia) in any of our patients whereas the consistently high VWF levels were compatible with an endothelial activation and/or damage." (PMID 33572417, 2021). "In mice, BjV caused thrombocytopenia in both Vwf-/- and C57BL/6 (background control) strains, and VWF:Ag levels tended to decrease in C57BL/6, demonstrating that thrombocytopenia was independent of the presence of plasma VWF." (PMID 34478462, 2021). "Studies revealed that platelet function in flowing blood is not impaired in cirrhosis patients, and the thrombocytopenia status could be balanced by elevated platelet adhesive protein von Willebrand factor (vWF) level and the inhibition of its regulator." (PMID 33407176, 2021). "Therefore, we proved that it is possible to use antibodies to inhibit metastasis without inducing thrombocytopenia by blocking the vWF-GPIbα interaction." (PMID 30223883, 2018). "Additionally, our study showed that excess VWF and ADAMTS13 deficiency are features of acute melioidosis, but are not the primary drivers of thrombocytopenia in melioidosis." (PMID 28296884, 2017). "However, the thrombocytopenia of melioidosis is likely not driven by excess VWF: other possible drivers include diffuse intravascular coagulation (DIC) and hemophagocytosis." (PMID 28296884, 2017). "However, if VWF were the main driver of thrombocytopenia in melioidosis, then it is surprising that VWF antigen, VWF propeptide and ADAMTS13 levels do not correlate with mortality." (PMID 28296884, 2017). "Additionally, excess VWF and ADAMTS13 deficiency are features of acute melioidosis, but are not the primary drivers of thrombocytopenia in melioidosis." (PMID 28296884, 2017). "Although the underlying mechanisms have yet to be fully elucidated, we can definitely conclude that there can be no consumption of large VWF multimers without thrombocytopenia, neither under basal conditions or after stress, nor during pregnancy, or after DDAVP infusion." (PMID 28640903, 2017).
Thrombocytopenia (continued). "Additionally, study results showed that excess VWF and ADAMTS13 deficiency are features of acute melioidosis, but are not the primary drivers of thrombocytopenia in melioidosis." (PMID 28296884, 2017). "Under circumstances in which VWF binds GPIbα in normal blood flow, such as type 2B VWD22, VWF binding may induce MSD unfolding and GPIb–IX-transduced signalling in the platelet and lead to thrombocytopenia." (PMID 27670775, 2016). "Thrombocytopenia and increased platelet clearance observed in von Willebrand disease-type 2B (VWD-2B) may be explained by platelet apoptosis triggered by the constitutive binding of VWF to its receptor, glycoprotein Ib (GPIb)." (PMID 26645283, 2015). "Our work has contributed to the explanation at least partially of the mechanisms behind these two observations: increased ADAMTS-13 proteolysis for the lack of HMW multimers and enhanced phagocytosis of mutant VWF-bound platelets by macrophages for the thrombocytopenia." (PMID 25297919, 2015). "In studies performed prior to this discovery, normal pigs and dogs injected with botrocetin developed thrombocytopenia, microthrombi in lungs and spleen but not kidney or brain, and initial depletion of VWF multimers followed by the appearance of ultra large VWF multimers during recovery." (PMID 22091368, 2010). "However in early experimental malaria, raised vWF and thrombocytopenia were not accompanied by a change in ADAMTS13 activity." (PMID 19450727, 2009). "Thus, the presence of VWF may be a minor contributing factor, but not a determinant factor, for BjV-induced thrombocytopenia." (PMID 34478462, 2021). "The binding of the coagulation protein von Willebrand factor (VWF) to the platelet membrane and removal of sialic acid (desialylation) are two well-known mechanisms of platelet clearance, but whether these conditions also contribute to thrombocytopenia in dengue infection is unknown." (PMID 30849118, 2019). "Altogether, these results showed that botrocetin had no participation in the development of thrombocytopenia, and that botrocetin and SVMP had a more evident role in the consumption and cleavage of VWF." (PMID 34478462, 2021). "The laboratory hallmark of the most typical and frequent forms of type 2B is the heightened RIPA with mild to moderate thrombocytopenia, mildly reduced to normal FVIII and VWF:Ag, reduced VWF:RCo and absence of the HMW multimers in plasma." (PMID 28394285, 2017). "Remarkably, giant platelets and thrombocytopenia can also be observed in patients lacking FLNa or with a defect in FLNa content as well as in patients with VWD-type 2B, characterized by an increased affinity of VWF for GPIb-IX-V (see section VWF and pathologies)." (PMID 25297919, 2015).